NLRP3 (NLR family pyrin domain containing 3)
Diseases named in the same sentence as NLRP3 in open-access papers (continued):
Sharing a sentence is not in itself a finding about the gene and the disease.
epilepsy (continued). "Since the role of the NLRP3 inflammasome pathway in the pathogenesis and progression of epilepsy has been well documented, the development of NLRP3 inhibitors as a potential therapeutic target for the treatment of seizures and epilepsy is urgently needed." (PMID 38892264, 2024). "Studies from Li and coworkers have reported that ibuprofen may have antiepileptic and neuroprotective effects in the rat model of PTZ-induced epilepsy via inhibiting NLRP3 inflammasome activation." (PMID 38892264, 2024). "Huperzine A, a naturally occurring sesquiterpene alkaloid and valproic acid, and one of the most prescribed medications against epilepsy, has been shown to inhibit activation of the NLRP3 inflammasome in the rat KA-induced model of epilepsy in a ROS-dependent manner." (PMID 38892264, 2024). "Our preliminary data encourage the further development of more potent NLRP3 inhibitors based on this chalcone scaffold, which could lead to the development of novel treatments for epilepsy and other inflammatory diseases." (PMID 38892264, 2024). "For example, NLRP3 inflammasome is involved in epilepsy progression." (PMID 37188671, 2023). "Moreover, NF-κB (P65) signaling would be activated, leading to the upregulated transcription of inflammasome-related components, such as NLRP3, pro-IL-1, and pro-IL-18 in epilepsy." (PMID 37367679, 2023). "This indicated that GPR120 also plays a role in the regulation of epilepsy through NLRP3." (PMID 35624482, 2022). "We hypothesize that by reducing NLRP3 activation in the neonatal brain, the inhibition of IL-1β expression would substantially ameliorate epilepsy after HIBD, as well as improve learning and memory abilities." (PMID 34046147, 2021). "Thus, ketosis suppresses inflammatory signaling (e.g., NLRP3/TLR4/IL-1R/NF-κB) signaling pathways and proinflammatory cytokines/enzymes (e.g., IL-1β and COX-2) that are linked pathophysiologically to epilepsy and other seizure disorders." (PMID 31680801, 2019). "As the most classic inflammasome, NLRP3 is involved in many neurological diseases such as Alzheimer’s disease, cerebrovascular disease, and epilepsy." (PMID 31417409, 2019). "Indeed, NLRP3 inhibition was already reported to provide neuroprotection in a kindling model of epilepsy." (PMID 29996878, 2018). "NLRP3 inflammasome is proposed to regulate inflammation in several neurological diseases, but its role in epilepsy remains largely unknown." (PMID 25516224, 2014). "A positive correlation between NLRP3 and ERS has been observed in several models of epilepsy, including temporal lobe epilepsy, and in human brain tissues from patients with epilepsy, suggesting that it may be an underlying mechanism in the development of seizures." (PMID 38892264, 2024). "Given the possible impact of GPR120 on epilepsy via other signaling pathways, we further add the inhibitor of Caspase-1 on the basis of GPR120 knockdown, trying to verify whether inhibiting the activation of NLRP3 can rescue the impact of GPR120 knockdown on epilepsy." (PMID 35624482, 2022). "Moreover, the TLR4/MYD88/NF-κB/NLRP3 inflammasome pathway may be an important target for epilepsy treatment." (PMID 34421582, 2021). "In particular, seizures were effectively controlled by decreasing the levels of AIM2 and NLRP3 and NLRP1 in a mouse model of kainic acid-induced epilepsy." (PMID 40217546, 2025). "In a study of human focal epilepsy, investigators found an increased number of NLRP3-expressing CD3+ and CD14+ cells in peripheral blood mononuclear cells from epilepsy patients." (PMID 40217546, 2025). "Laboratory studies from epilepsy have shown that the levels of inflammasomes (NLRP1, NLRP3, caspase 1, IL-1β, ASC, AIM2, gasdermin D, IL-18, intracellular calcium ion, sTNFr2) were also elevated." (PMID 40217546, 2025). "In the amygdala-ignited rat epilepsy model, knockdown of NLRP1, NLRP3 and Caspase 1 genes by using siRNA technology also reduced epileptic activity." (PMID 40217546, 2025).
epilepsy (continued). "Meanwhile, seizures can be rescued by using caspase-1 (downstream effector molecules of NLRP3) inhibitors, further proving that GPR120 regulates epilepsy via NLRP3 inflammation." (PMID 35624482, 2022). "Hence it was proposed that NLRP3 may be a target for treatment in epilepsy." (PMID 34112082, 2021). "Hence, negative regulation of NLRP3 inflammasome activity is essential for controlling epileptogenesis and reducing seizures, and may therefore be a target for the treatment of epilepsy." (PMID 31417409, 2019). "In a mouse epilepsy protocol, the gene expression of P2X7, NLRP3, and IL-1β was increased." (PMID 40732240, 2025). "A case-control study investigating the correlation between NLRP3 expression and HMGB1 levels in the serum of children with febrile epilepsy revealed that serum levels of HMGB1, NLRP3, caspase-1, IL-1β, IL-6, and TNF-α were significantly higher in children with epilepsy compared to controls." (PMID 40688353, 2025). "Liraglutide treatment reduced NLRP3 levels in rats with epilepsy, although no significant changes were observed." (PMID 39457518, 2024). "Additionally, an increasing number of researchers have reported that inhibition of the NLRP3 pathway can ameliorate epileptic seizure episodes and cognitive dysfunction; therefore, the NLRP3 pathway could be considered a potential treatment target for epilepsy." (PMID 38662166, 2024). "The role of NLRP3 in neuroinflammation in combination with its broad range of mediators indicates that GPR120 might regulate neuroinflammation and manifest its protective effect in epilepsy through NLRP3-dependent signaling pathway." (PMID 35624482, 2022). "Similar experimental work in non-epilepsy models suggested that ketone body anti-inflammatory effects may be mediated by hydroxy-carboxylic acid receptor 2 (HCA2) and/or inhibition of the innate immune sensor NOD-like receptor 3 (NLRP3) inflammasome." (PMID 30096755, 2018). "In the kainic acid epilepsy mouse model, the results of the three studies collectively point to the signaling pathways of NLRP1, NLRP3, absent in melanoma 2 (AIM2), caspase 1, and ASC playing a key role in the activation of inflammation during epilepsy." (PMID 40217546, 2025).
preeclampsia (44 papers, 2015 to 2026). Preeclampsia is a hypertensive disorder of pregnancy that is characterized by new-onset hypertension with proteinuria presenting after 20 weeks of gestation, and depending on mild or severe forms may initially present with severe headache, visual disturbances, and hyperreflexia. "Uric acid enhances trophoblast IL-1β production via activation of the NLRP3 inflammasome and production of IL-1β, which are implicated in the pathogenesis of preeclampsia and adverse pregnancy outcome." (PMID 36560538, 2022). "These recent contributions suggest that NLRP3 inflammasome activation is implicated in the inflammatory processes associated with the pathophysiology of preeclampsia." (PMID 34831052, 2021). "This suggests that NLRP3 inflammasomes can also cause abnormal inflammatory responses related to abortion or preeclampsia." (PMID 33854691, 2021). "Cholesterol crystal mediated NLRP3 inflammasome activation is central to cardiovascular disease and the pathway has been implicated in placental inflammation in preeclampsia." (PMID 33117348, 2020). "We have previously shown that the NLRP3 inflammasome is active in the placenta and associated with preeclampsia, with a central involvement of trophoblasts." (PMID 33117348, 2020). "Preeclampsia with normal fetal growth was associated with increased expression of NLRP3 and IL-1β, particularly in decidual areas of close maternal-fetal interaction." (PMID 33117348, 2020). "In addition, we observed a positive enrichment of NLRP3 mediated inflammasomes, which are implicated in various pregnancy-related dysfunctional states, including preeclampsia." (PMID 39039088, 2024). "The monitoring for NLRP3 in peripheral blood may be a potential, prospectively identifying risk factor for preeclampsia." (PMID 37226086, 2023). "We aimed to determine the effects of IL11 on inflammasome activation in human and mouse placenta and whether loss of NLRP3/ASC-inflammasome activity could prevent IL11-induced preeclampsia." (PMID 37292200, 2023). "In addition, damage-associated molecular patterns induce production of NLRP3, which plays a key role in sterile inflammation and is implicated in pregnancy dysfunction, including preeclampsia." (PMID 36496806, 2022). "However, we also found that silencing NR4A2 increased the expression of NLRP3, which is a key regulator of the inflammatory response and has been implicated in preeclampsia pathogenesis." (PMID 34667209, 2021). "MiR-223 is a microRNA which intervenes in different processes including infections, inflammation and preeclampsia, via NLRP3 targeting." (PMID 41561632, 2025). "Noteworthy, the inflammasome NLR family pyrin domain containing 3 (NLRP-3), abundantly expressed in the human placenta, has been studied in preeclampsia, recurrent pregnancy loss and preterm delivery." (PMID 40526637, 2025). "Activating the NLRP3 inflammasome disrupts the inflammatory microenvironment in the uterus, which leads to excessive inflammation at the maternal–fetal interface in rat preeclampsia." (PMID 38903689, 2024). "This pathway is also involved in the placental changes seen in preeclampsia, miscarriage, and gestational diabetes, and it involves activation of the intracellular innate immunity receptor NLRP3, with subsequent production of Caspase 1, IL-1β, and IL-18." (PMID 37047793, 2023). "Activation of the inflammasome-NLRP3 pathway is involved in gestational diseases such as preeclampsia and gestational diabetes." (PMID 37047793, 2023). "There is substantial evidence for placental inflammasome activation, particularly NLRP3 inflammasome activation, and pyroptosis in early-onset preeclampsia." (PMID 37292200, 2023). "As far as I know, this is the first study to the current time that has assessed NLRP3 in the monocytes in patients with early-onset preeclampsia and compared them with normotensive pregnant women." (PMID 37226086, 2023).
preeclampsia (continued). "There is a higher endogenous activation of NLRP1/NLRP3 inflammasomes in the monocytes from preeclamptic women than normotensive pregnant women, but Silibinin can inhibit NLRP1/NLRP3 inflammasomes in monocytes from pregnant women with preeclampsia." (PMID 36560538, 2022). "In preeclampsia patients who have a high level of sENG and inflammatory cytokines in their plasma, NLRP3-mediated inflammasome activation has been shown in their placenta." (PMID 35163148, 2022). "In this study, we detected lower expression levels of MEG3 and β-Catenin and higher expression of nod-like receptor pyrin domain-containing 3 (NLRP3) in placental tissues of pregnant women with severe preeclampsia (sPE) than in normal pregnancies." (PMID 36310595, 2022). "Several studies have suggested that the expression of NLRP3 is substantially increased in placentas from PE and is tightly related to the well-established pathogenesis of preeclampsia, such as sterile inflammation and oxidative stress." (PMID 36310595, 2022). "Furthermore, DAMP-induced NLRP3 levels have been extensively investigated in placental inflammation and dysfunction through the accumulation of cytokines (e.g., IL-1β), all of which were implicated in various pregnancy complications including preeclampsia and spontaneous pre-term labour." (PMID 35563719, 2022). "Placenta from women with preeclampsia shows an upregulation of NLRP3 compared to normotensive pregnant women, and higher expression of NLRP3 inflammasome exaggerates the inflammatory state in preeclampsia." (PMID 36496806, 2022). "The current study revealed that MEG3 regulates trophoblast function and inflammation through the Wnt/β-Catenin/NLRP3 axis and provided new insights into the pathogenesis of preeclampsia." (PMID 36310595, 2022). "The interaction between alarmin-induced activation of placental NLRP3 inflammasome and the resulting placental inflammation presented in pregnancy complications such as preeclampsia has been shown by in vivo studies." (PMID 34831052, 2021). "We have previously demonstrated a placental role for the NLRP3 inflammasome in preeclampsia combined with FGR, while the decidual contribution presented here was apparent in preeclampsia without FGR." (PMID 33117348, 2020). "The identification of decidual cholesterol crystals and increased decidual NLRP3 inflammasome expression in preeclampsia with normal fetal growth further substantiates the pathophysiological link between preeclampsia and CVD." (PMID 33117348, 2020). "In the decidua, increased cholesterol accumulation in preeclampsia and NLRP3 inflammasome expression in cultured cells has been shown." (PMID 33117348, 2020). "In the field of Reproductive Biology, miR-520c-3p has been shown to inhibit the NLRP3 inflammasome in preeclampsia." (PMID 32047476, 2020). "This article aims to delineate the role of NLRP3 in the development of preeclampsia, its symptoms, and complications." (PMID 32650532, 2020). "The NLRP3 inflammasome expression pattern in decidua further points to interesting pathophysiological differences between preeclampsia subgroups." (PMID 33117348, 2020). "The NLRP3 inflammasome pathway in preeclampsia has been recently reviewed and mechanistically illustrated." (PMID 33117348, 2020). "These cells stimulation with MSU demonstrates that uric acid plays a role in NLRP3 inflammasome activation, suggesting the participation of this inflammatory complex in the pathogenesis of preeclampsia." (PMID 26053021, 2015). "In the present study, the demonstrated capacity of NLRP3 inflammasome in inducing IL-1β production suggests a role for this mechanism in the systemic inflammatory response observed in preeclampsia." (PMID 26053021, 2015). "Moreover, previous studies have demonstrated activation of the inflammasome-NLRP3 pathway in placental alterations observed in preeclampsia, gestational diabetes, and miscarriage." (PMID 37047793, 2023).
preeclampsia (continued). "A recent in vitro study showed that activation of the P2X7 receptor after incubation with BPA has been observed in human placental cells, leading to different pathways involved in producing preeclampsia and preterm delivery, through activation of the NLRP3 inflammasome and apoptosis." (PMID 36902016, 2023). "All of the experiments showed significantly lower expression of β-Catenin and higher expression of NLRP3 in preeclampsia placental tissues compared to normal pregnancies, implying that they might have functions related to preeclampsia." (PMID 36310595, 2022). "In the pathogenesis of preeclampsia, the activation of NLRP3 by DAMPs leads to an increased blood pressure through sympathetic nervous system activation, activation of the renin–angiotensin–aldosterone system (RAAS), tubulointerstitial inflammation, and placental abruption." (PMID 35563719, 2022). "A recent study has found that inhibition of the trophoblast TLR4/NF-κB/PFKFB3 signaling pathway to correct glycometabolic reprogramming and NLRP3 inflammation-induced pyroptosis may be a treatment approach for preeclampsia." (PMID 36589684, 2022). "Moreover, studies have confirmed that the expression of the NLRP3 inflammasome is increased in the placenta of preeclampsia patients." (PMID 33854691, 2021). "Growing evidence supports the clinical benefits and anti-inflammatory effects of drugs targeting the NLRP3 inflammasome and IL-1β pathway in several diseases, but whether they are pregnancy-safe and effective in preeclampsia needs to be determined." (PMID 33117348, 2020). "Preeclampsia without FGR was associated with increased trophoblast dependent NLRP3 and IL-1β expression, particularly in the decidual areas of trophoblast and leukocyte proximity." (PMID 33117348, 2020). "Despite many unknowns in the pathomechanism of PE development studies proving the crucial role of NLRP3 in that process and delineating DAMPs, which can activate the inflammasome can be a source of great change in the therapy and prophylaxis of preeclampsia." (PMID 32650532, 2020). "Therefore, crystal-induced NLRP3 inflammasome activation theory can facilitate the development of effective prophylaxis and treatment of preeclampsia." (PMID 32650532, 2020). "This points to divergent NLRP3 inflammasome activation in preeclampsia subgroups." (PMID 33117348, 2020). "However, the precise molecular details of NLRP3 inflammasome in response to uric acid in preeclampsia remain to be elucidated." (PMID 26053021, 2015). "Preeclampsia is associated with abnormal activation of cells from the innate immune system, and the peripheral blood monocytes from preeclamptic pregnant women have higher endogenous activation of NLRP1/NLRP3 inflammasomes than that from normotensive pregnant women." (PMID 37228386, 2023). "The increased decidual NLRP3 and IL-1β expression associated with preeclampsia with normal fetal growth could not be explained by differences in decidual leukocyte and trophoblast density." (PMID 33117348, 2020). "To establish the relationships between MEG3, β-Catenin, NLRP3 and the pathogenesis of preeclampsia, we first measured the expression levels of MEG3, β-Catenin and NLRP3 in placental tissues by qRT‒PCR." (PMID 36310595, 2022). "In our study, MEG3 and β-Catenin expression decreased and NLRP3 expression increased in HTR-8/SVneo cells stimulated by H/R, similar to the levels observed in the placental tissue of preeclampsia." (PMID 36310595, 2022). "HO-1 and eNOS levels were decreased, and NLRP3 and HMGB1 levels were increased in the preeclampsia model, resulting in the elevation of oxidative stress and pyroptosis in the preeclampsia model." (PMID 36153499, 2022). "The novel identification of decidual cholesterol crystals combined with increased NLRP3 inflammasome expression presents a novel link between the pathophysiology of CVD and preeclampsia." (PMID 33117348, 2020).
preeclampsia (continued). "Therapeutic inhibition of the ASC or NLRP3 inflammasome in women with elevated serum IL11 in early pregnancy could prevent IL11-induced placental inflammation and subsequent preeclampsia." (PMID 37292200, 2023). "Inhibition of ASC/NLRP3 inflammasome activity could prevent IL11-induced inflammation and fibrosis in various disease states including preeclampsia." (PMID 37292200, 2023). "MiR-223-3p suppressed NLRP3 inflamariomes activation, downstream inflammatory factors secretion and pyroptosis in LPS-induced HTR8/SVneo cells indicating that miR-223-3p could serve as an anti-inflammatory factor in preeclampsia." (PMID 38448875, 2024). "A closer look at decidual tissue with trophoblast and maternal leukocytes in proximity showed that the expression intensity of NLRP3 and IL-1β was significantly increased in preeclampsia without FGR compared to normal pregnancies (NLRP3 P = 0.017 and IL-1β P = 0.031)." (PMID 33117348, 2020). "Our findings suggest that decidual accumulation of cholesterol crystals may activate the NLRP3 inflammasome and contribute to decidual inflammation and that this pathway is strengthened in areas with close maternal-fetal interaction in preeclampsia without FGR." (PMID 33117348, 2020).